RNU1-8P (RNA, U1 small nuclear 8, pseudogene)
Synonyms: RNU1-8
Gene: Small nuclear RNA gene on chromosome 1 (7,219,360 to 7,219,524, forward strand). Ensembl gene ENSG00000207056.
Homologues: Orthologues: chimpanzee U1 (97% identical), macaque U1 (88% identical), guinea pig U1 (79% identical). Paralogues in human: RNVU1-7 (85% identical), RNU1-1 (85% identical), RNU1-2 (85% identical), RNU1-27P (85% identical), RNU1-28P (85% identical), RNU1-3 (85% identical), RNU1-4 (85% identical), RNVU1-18 (85% identical), RNVU1-29 (85% identical), U1 (85% identical), RNU1-89P (84% identical), RNVU1-28 (84% identical), and 134 more.